CILK1 (ciliogenesis associated kinase 1)
Description:
Required for ciliogenesis. Phosphorylates KIF3A (By similarity). Involved in the control of ciliary length. Regulates the ciliary localization of SHH pathway components as well as the localization of IFT components at ciliary tips (By similarity). May play a key role in the development of multiple organ systems and particularly in cardiac development (By similarity). Regulates intraflagellar transport (IFT) speed and negatively regulates cilium length in a cAMP and mTORC1 signaling-dependent manner and this regulation requires its kinase activity (By similarity).
Synonyms: hICK; LCK2; MRK; ICK; KIAA0936; MGC46090; CED6; ECO; EJM10
Tractability: Small molecule: a high-quality ligand is known; it belongs to a druggable protein family. PROTAC: ubiquitination databases record sites on it; a small molecule that binds it is known.
Target class: Enzyme; Kinase; CMGC protein kinase group; CMGC protein kinase MAK; Protein Kinase; CMGC protein kinase RCK family
Gene: Protein-coding gene on chromosome 6 (53,001,279 to 53,061,824, reverse strand). Ensembl gene ENSG00000112144.
Subcellular location: Nucleus; Cytoplasm, cytosol; Cell projection, cilium; Cytoplasm, cytoskeleton, cilium basal body; Cytoplasm (Isoform 2)
Subcellular location (Human Protein Atlas): Golgi apparatus; Vesicles; Primary cilium; Primary cilium tip
Gene Ontology:
Molecular function: ATP binding; magnesium ion binding; protein binding; protein kinase activity; protein serine kinase activity; protein serine/threonine kinase activity
Biological process: cilium assembly; intracellular signal transduction; protein phosphorylation; intraciliary anterograde transport; intraciliary retrograde transport; intraciliary transport; signal transduction
Cellular component: ciliary tip; cilium; cytoplasm; nucleus; ciliary basal body; ciliary base; cytosol
Genetic constraint (gnomAD): Loss-of-function variants: 39 observed, 65.82 expected, observed/expected ratio (o/e) 0.59, 90% interval 0.46 to 0.77. The upper end of that interval is the gene's LOEUF score, 0.77, which puts it in group 3 of 6, group 1 being the genes least tolerant of losing a copy. Missense variants: 536 observed, 666.16 expected, observed/expected ratio (o/e) 0.8, 90% interval 0.75 to 0.86. Synonymous variants: 228 observed, 245.99 expected, observed/expected ratio (o/e) 0.93, 90% interval 0.83 to 1.03.
Homologues: Orthologues: chimpanzee CILK1 (99% identical), macaque CILK1 (99% identical), dog CILK1 (94% identical), rabbit CILK1 (93% identical), guinea pig CILK1 (92% identical), pig CILK1 (92% identical), mouse Cilk1 (86% identical), rat Cilk1 (86% identical), tropical clawed frog cilk1 (61% identical), Caenorhabditis elegans pmk-2 (19% identical), Caenorhabditis elegans pmk-1 (17% identical), Drosophila melanogaster SRPK (17% identical), and 8 more. Paralogues in human: MAK (56% identical), MOK (23% identical), MAPK6 (22% identical), MAPK15 (19% identical), MAPK7 (19% identical), MAPK1 (19% identical), MAPK12 (19% identical), MAPK14 (19% identical), MAPK10 (19% identical), MAPK9 (19% identical), MAPK13 (19% identical), MAPK8 (19% identical), and 7 more.
Diseases named in the same sentence as CILK1 in open-access papers:
CILK1 is named in the same sentence as 33 diseases in open-access papers, as found by Europe PMC text mining. Sharing a sentence is not in itself a finding about the gene and the disease. The quoted sentences say what the papers report.
ciliopathies (19 papers, 2014 to 2025). "When considering other types of CED, a key observation is that nearly all genes implicated in its etiology, including CILK1, are associated with multiple ciliopathy phenotypes." (PMID 40615527, 2025). "Loss of Cilk1 results in severe ciliopathy phenotypes, including polydactyly, edema, and cleft palate." (PMID 41320695, 2025). "Mutations in human CILK1 (ciliogenesis associated kinase 1) are linked to ciliopathies and epilepsy." (PMID 39120290, 2024). "The homozygous mutations (e.g., R272Q) in the catalytic domain of CILK1 abolished kinase activity, impaired cilia length control and Hedgehog signaling, and caused ciliopathy phenotypes." (PMID 39120290, 2024). "Mutations in the human CILK1 gene have been associated with ciliopathies, a group of human genetic disorders with defects in the primary cilia." (PMID 38725848, 2024). "Human CILK1 mutations that compromise the kinase activity are associated with ciliopathies that manifest in longer cilia and abnormal ciliary signaling." (PMID 35897693, 2022). "Collectively, these results support the general conclusion that CILK1 mutations causing exuberant cilia growth result in ciliopathy, whereas CILK1 mutations preserving normal cilia growth are associated with normal development." (PMID 34445580, 2021). "Complete Cilk1 deletion also recapitulates ciliopathy phenotypes and causes exuberant cilia growth, consistent with the role of CILK1 in restricting cilia formation and growth." (PMID 34445580, 2021). "Inactivating mutations in the human CILK1 gene (R272Q) cause neonatal–lethal human ciliopathies, such as endocrine-cerebro-osteodysplasia (ECO) syndrome and ECO-like syndromes." (PMID 34445580, 2021). "Mutations in CILK1 are associated with ciliopathies and are also linked to juvenile myoclonic epilepsy (JME)." (PMID 32178256, 2020). "In mice, both Cilk1 knock-out and Cilk1 knock-in mutations have recapitulated human ciliopathies." (PMID 38523660, 2024). "Ciliogenesis-associated kinase 1 (CILK1) plays a key role in the ciliogenesis and ciliopathies." (PMID 38725848, 2024). "Accordingly, ciliopathy phenotypes in MEFs require deletion or inactivation of both Cilk1 alleles." (PMID 39120290, 2024). "Ciliopathies caused by CILK1 mutations show longer cilia and abnormal Hedgehog signaling." (PMID 35897693, 2022). "CILK1 mutations cause a wide spectrum of human diseases collectively called ciliopathies." (PMID 34445580, 2021). "As a MAPK- and CDK-like kinase, CILK1 is well established for its involvement in ciliogenesis and development of ciliopathies." (PMID 38725848, 2024). "Remarkably, one of the most downregulated genes at 36 hpi is CILK1 (−1.96 log2FC), which is involved in ciliopathies." (PMID 38932231, 2024). "Mutations of CILK1 found in JME and ciliopathies are scattered across the N-terminal catalytic domain (NTD) and the C-terminal non-catalytic domain (CTD)." (PMID 32178256, 2020). "Understanding how CILK1 and MAK regulate the IFT turnaround process by phosphorylating the downstream target(s) could reveal the extent to which the activation of CCRK-CILK1/MAK kinase signaling can be more generally applicable to treat human ciliopathies." (PMID 40636449, 2025). "How CILK1 dysfunction leads to ciliopathies is still poorly understood." (PMID 39120290, 2024). "CILK1 variants associate with both JME (red) and human ciliopathies (purple)." (PMID 34445580, 2021). "The CILK1 variant is located in the C-terminal non-catalytic domain and is predicted to cause a truncated protein, which differs in variant type and location from the CILK1-associated ciliopathies of ECO and SRPS." (PMID 40615527, 2025).
ciliopathies (continued). "Patients with mutations in the genes encoding IFT-A, cytoplasmic dynein-2 components, and CILK1 exhibited a similar spectrum of ciliopathy symptoms, suggesting a functional relationship among IFT-A, cytoplasmic dynein-2, and CILK1." (PMID 40636449, 2025). "Recently, CILK1 and MAK have emerged as potential therapeutic targets for human diseases including ciliopathies and age-related obesity." (PMID 40636449, 2025). "Recently, CILK1 and MAK have emerged as potential therapeutic targets for the treatment of ciliopathies and age-related obesity." (PMID 40636449, 2025).
epilepsy (5 papers, 2020 to 2025). A brain disorder characterized by episodes of abnormally increased neuronal discharge resulting in transient episodes of sensory or motor neurological dysfunction, or psychic dysfunction. "To evaluate the impact of an epilepsy-associated mutation, CILK1 A615T, on primary cilia and ciliary Hedgehog signaling, we used CRISPR/Cas9 to genetically engineer mutations in exon 13 of mouse Cilk1." (PMID 39120290, 2024). "Herein, we investigated whether mice harboring either a heterozygous null Cilk1 (Cilk1+/−) mutation or a heterozygous loss-of-function Cilk1 mutation (Cilk1R272Q/+) have epilepsy." (PMID 34445580, 2021). "In contrast, CILK1 variants exhibited no reduction in ciliogenesis; instead, both an inactive mutant (R272A) and epilepsy variants of CILK1 showed significant increases in ciliation." (PMID 32178256, 2020). "Initially, EJM10 was attributed to CILK1 haploinsufficiency; however, heterozygous null or ECO-associated p.Arg272Gln variants in mice did not result in epilepsy." (PMID 40615527, 2025).
juvenile myoclonic epilepsy (4 papers, 2020 to 2025). "While several CILK1 heterozygous variants have been recently linked to juvenile myoclonic epilepsy (JME), it remains unclear whether these mutations cause seizures." (PMID 34445580, 2021). "Pathogenic variants of CILK1 were recently linked to juvenile myoclonic epilepsy (JME)." (PMID 32178256, 2020). "Here, we produced a knock-in mouse equivalent to the human CILK1 A615T variant identified in juvenile myoclonic epilepsy (JME)." (PMID 39120290, 2024). "Recently, an expansive genetic study linked multiple pathological CILK1 point mutations to juvenile myoclonic epilepsy (JME), the most commonly diagnosed Genetic Generalized Epilepsy." (PMID 34445580, 2021).
glioblastoma (3 papers, 2014 to 2024). The most malignant astrocytic tumor (WHO grade IV). "Interestingly, CILK1/ICK was found to mediate the effect of CDK20 on ciliogenesis in glioblastoma cells and it also regulates the inhibitory effect of fibroblast growth factor on cilia by interacting with FGFR3." (PMID 38523660, 2024).
breast carcinoma (2 papers, 2010 to 2024). "The data showed that the down-regulation of CILK1 promoted the killing effect of paclitaxel in breast cancer cells, as well as in the paclitaxel-resistant cells." (PMID 38725848, 2024). "Taken together, these data indicate that the elevated CILK1 not only facilitates the proliferation of breast cancer cells, also engages in the formation and maintenance of paclitaxel-resistance phenotype." (PMID 38725848, 2024). "Here, we report that the aberrant high-expression of CILK1 in breast cancer is required for tumor cell proliferation and chemoresistance." (PMID 38725848, 2024). "To investigate the clinic-pathological relevance of CILK1 in drug resistance, we detected the expression of phospho-CILK1 (Tyr-159) and total-CILK1 protein by IHC in a cohort of clinical breast cancer patients." (PMID 38725848, 2024). "By analysis of The Cancer Genome Atlas (TCGA) and Genotype-Tissue Expression (GTEx) databases, we observed an increased mRNA expression of CILK1 in a variety of human cancers including breast cancer, lung cancer, esophageal cancer and liver cancer etc.." (PMID 38725848, 2024). "Meanwhile, knockdown of CILK1 significantly slowed down the proliferation rate of all four breast cancer cell lines." (PMID 38725848, 2024). "CILK1 was positively expressed in almost all breast cancer specimens (96%), while 45% normal breast tissues were negative staining." (PMID 38725848, 2024). "Our data showed that the expression of CILK1 in four major breast cancer subtypes including Luminal A, Luminal B, HER2+ and Triple-negative, was significantly higher than that of adjacent normal breast tissues." (PMID 38725848, 2024). "In order to determine whether the inhibitory effects of CILK1-C30/28 on breast cancer cell proliferation rely on the repression of CILK1, cell viability assay was performed in vector control and CILK1-knockdown cells." (PMID 38725848, 2024). "Collectively, these data indicate that the expression of CILK1 is up-regulated in breast cancer, suggesting that it might play a role in breast cancer." (PMID 38725848, 2024). "Interestingly, CILK1 protein expression was not significantly linked to specific breast cancer subtype." (PMID 38725848, 2024). "Furthermore, 100% of breast cancer cases expressed phospho-CILK1, suggesting that the kinase activity of CILK1 might be required for breast cancer tumorigenicity." (PMID 38725848, 2024). "We used a panel of breast cancer cell lines, including MDA-MB-231 and BT-549 (Triple-negative), T47D (Luminal) and BT-474 (HER2+) to construct stable CILK1-knockdown clones." (PMID 38725848, 2024). "And, there was no apparent difference of CILK1 mRNA level among breast cancer subtypes based on Gene Expression Omnibus (GEO) databases." (PMID 38725848, 2024). "Based on our large-scale analyses on breast cancer patient specimens, the expression of total and phosphorylated CILK1 protein was revealed to highly accumulate in tumor cells, and the expression of CILK1 protein has no specificity in breast cancer subtypes." (PMID 38725848, 2024). "Subsequently, the analysis of CILK1 expression in a panel of cultured breast cell lines indicated that it has much lower mRNA and protein levels in luminal A breast cancer cell line (MCF7) and non-tumorigenic breast cell line (MCF12a)." (PMID 38725848, 2024).
breast tumor (1 paper, 2024). "The results showed that the accumulation of phospho-CILK1 was also significantly up-regulated in breast tumor tissues, compared with the adjacent non-cancerous tissues." (PMID 38725848, 2024).
cranioectodermal dysplasia (1 paper, 2025). Cranioectodermal dysplasia (CED) is a rare developmental disorder characterized by congenital skeletal and ectodermal defects associated with dysmorphic features, nephronophthisis, hepatic fibrosis and ocular anomalies (mainly retinitis pigmentosa). "In conclusion, we demonstrate that the homozygous frameshift variant in the non-catalytic domain of CILK1 causes cranioectodermal dysplasia through disruption of retrograde IFT and ciliary dynamics." (PMID 40615527, 2025).
lung carcinoma (1 paper, 2024). "We found the gene expression of CILK1 was up-regulated in lung cancer versus normal lung tissues by bio-informatic analyses." (PMID 38725848, 2024). "Pharmacological inhibition or genetic silencing of CILK1 enhances chemotherapy regents-induced cytotoxicity in breast and lung cancer cells." (PMID 38725848, 2024). "To discern the relevance of CILK1 in lung cancer chemoresistance, we amassed a collection of specimens from 18 SCLC patients that were treated with united platinum/etoposide chemotherapy." (PMID 38725848, 2024).
Obesity (1 paper, 2025). Accumulation of substantial excess body fat. "Given that loss-of-function of Cilk1 inhibits the IFT turnaround process at ciliary tips, how Cilk1 knockdown in hypothalamic neurons can improve ciliary function to suppress obesity awaits future studies." (PMID 40636449, 2025).
retinal degeneration (1 paper, 2025). Degeneration of the retina. "Loss of Ccrk causes severe retinal degeneration, resembling that observed in Cilk1 and Mak-double-knockout retinas." (PMID 40636449, 2025). "Administration of a small-molecule inhibitor of FGFRs, which negatively regulates CILK1 activity, suppresses retinal degeneration observed in RP model Mak-deficient mice." (PMID 40636449, 2025).
small cell lung carcinoma (1 paper, 2024). Small cell lung cancer (SCLC) is a highly aggressive malignant neoplasm, accounting for 10-15% of lung cancer cases, characterized byrapid growth, and early metastasis. "CILK1 is also indicated to be responsible for the chemoresistance of small-cell lung cancer cells." (PMID 38725848, 2024).
cancer (6 papers, 2010 to 2024). A tumor composed of atypical neoplastic, often pleomorphic cells that invade other tissues. "Pharmacological inhibition or genetic silencing of CILK1 arrests tumor cell cycle progression and proliferation as well as reduces cancer cell viability." (PMID 38725848, 2024). "Overall, we reveal CILK1 as the prognostic marker and therapeutic target for cancer, and presented two CILK1-specific inhibitors supported by multiple evidences." (PMID 38725848, 2024). "Although CILK1 plays an essential role in regulating the function of cilia, its functional role in cancer is poorly defined 3-6." (PMID 38725848, 2024). "Alvocidib, a semi-synthetic flavone related to a natural product extracted from Indian plants, has been shown to be a potent inhibitor of CILK1 in cells, suggesting a potential use for targeting PCs in cancer." (PMID 37510333, 2023). "Our data strongly support the conception that CILK1 plays as a driver of cancer progression." (PMID 38725848, 2024). "Targeting CILK1/ERK1 signaling would provide a promising option for the treatment of cancer." (PMID 38725848, 2024). "Our data highlight the importance of CILK1 in cancer, implicating that targeting CILK1/ERK1 might offer therapeutic benefit to cancer patients." (PMID 38725848, 2024).
tumor (6 papers, 2013 to 2025). "Our findings indicate that CILK1 cooperates with MEK to maintain the high-level of activation of ERK1 in tumor cells." (PMID 38725848, 2024). "Two small-molecule compounds are identified as the selective inhibitors of CILK1 and demonstrated to show robust anti-tumor efficacy in combination with chemotherapy." (PMID 38725848, 2024). "Altogether, these data support the contention that selective CILK1 inhibitors exhibit strong cytotoxicity to tumor cells and are able to potentiate the pro-apoptosis effect of chemotherapeutic reagents." (PMID 38725848, 2024). "Results showed that silencing of CILK1 robustly inhibited the tumor cell growth potential, and significantly reduced the size and weight of tumors in comparison with the vector control group." (PMID 38725848, 2024). "Two compounds, CILK1-C30 and CILK1-C28, were identified with selective inhibitory effects towards the Tyr-159/Thr-157 dual-phosphorylation of CILK1, pharmacological inhibition of CILK1 significantly suppressed tumor cell proliferation and overcame chemoresistance in multiple experimental models." (PMID 38725848, 2024). "Here, our data uncover the key role of CILK1 in the tumor progression and chemoresistance." (PMID 38725848, 2024). "It remains completely unclear whether CILK1 is required for tumor cell proliferation." (PMID 38725848, 2024). "It remains totally unclear whether CILK1 is involved in tumor progression and therapy resistance." (PMID 38725848, 2024).
CILK1 also shares sentences with these, for which no sentence is quoted: colon cancer (4 papers); colorectal cancer (3); retinitis pigmentosa (2); and type 2 diabetes (1); cleft palate (1); colorectal tumors (1); ECO syndrome (1); esophageal cancer (1); gastric cancer (1); glioma (1); intestinal cancer (1); intestinal diseases (1); lip (1); liver cancer (1); malnutrition (1); prostate carcinoma (1); retinal cancer (1); Seizure (1); short rib-polydactyly syndrome (1); stomach cancer (1).